PGM5 (phosphoglucomutase 5)
Description:
Component of adherens-type cell-cell and cell-matrix junctions. Positively regulates maturation and alignment of myofibrils, also promotes organization of sarcomeres (By similarity). Has no phosphoglucomutase activity in vitro.
Synonyms: PGMRP
Tractability: Antibody: its Gene Ontology location is reachable by antibodies, with high confidence; UniProt places it where antibodies can reach, with medium confidence.
Gene: Protein-coding gene on chromosome 9 (68,328,308 to 68,535,009, forward strand). Ensembl gene ENSG00000154330.
Subcellular location: Cell junction, adherens junction; Cytoplasm, cytoskeleton; Cell membrane, sarcolemma
Subcellular location (Human Protein Atlas): Cytosol
Gene Ontology:
Molecular function: phosphoglucomutase activity; structural molecule activity; intramolecular phosphotransferase activity; magnesium ion binding
Biological process: myofibril assembly; striated muscle tissue development; carbohydrate metabolic process
Cellular component: adherens junction; costamere; cytoplasmic side of plasma membrane; focal adhesion; intercalated disc; sarcolemma; spot adherens junction; stress fiber; cell-substrate junction; dystrophin-associated glycoprotein complex; cytoskeleton; Z disc
Genetic constraint (gnomAD): Loss-of-function variants: 19 observed, 39.76 expected, observed/expected ratio (o/e) 0.48, 90% interval 0.33 to 0.7. The upper end of that interval is the gene's LOEUF score, 0.7, which puts it in group 2 of 6, group 1 being the genes least tolerant of losing a copy. Missense variants: 468 observed, 554.29 expected, observed/expected ratio (o/e) 0.84, 90% interval 0.78 to 0.91. Synonymous variants: 179 observed, 202.37 expected, observed/expected ratio (o/e) 0.88, 90% interval 0.78 to 1.
Homologues: Orthologues: chimpanzee PGM5 (99% identical), pig PGM5 (98% identical), rat Pgm5 (98% identical), mouse Pgm5 (98% identical), dog PGM5 (97% identical), guinea pig PGM5 (97% identical), rabbit PGM5 (94% identical), macaque PGM5 (91% identical), tropical clawed frog pgm5 (83% identical), zebrafish pgm5 (77% identical), Caenorhabditis elegans pgm-1 (53% identical), Drosophila melanogaster Pgm1 (49% identical). Paralogues in human: PGM1 (65% identical), PGM2L1 (20% identical), PGM2 (19% identical), PGM3 (12% identical), HPRT1 (9% identical), PRTFDC1 (9% identical).
Diseases named in the same sentence as PGM5 in open-access papers:
PGM5 is named in the same sentence as 29 diseases in open-access papers, as found by Europe PMC text mining. Sharing a sentence is not in itself a finding about the gene and the disease. The quoted sentences say what the papers report.
colorectal cancer (8 papers, 2017 to 2022). A primary or metastatic malignant neoplasm that affects the colon or rectum. "PGM5 is a diagnostic and prognostic biomarker independently associated with the survival of patients with liver cancer and colorectal cancer." (PMID 34092242, 2021). "Recent studies found that PGM5 expression is decreased in liver cancer and colorectal cancer, and low PGM5 levels are associated with patients’ poor overall survival." (PMID 34616611, 2021). "For example, PGM5 was identified as a diagnostic and prognostic biomarker in liver and colorectal cancers." (PMID 33376725, 2020). "As well, PGM5 is reported to inhibit the proliferation, invasion and migration abilities of colorectal cancer cells." (PMID 34616611, 2021). "The present study indicated that PGM5 had lower expression in cancerous liver tissues than adjacent normal tissues, similar to the results of a previous study of colorectal cancer." (PMID 31218127, 2019). "PGM5 is downregulated in hepatocellular carcinoma and colorectal cancer." (PMID 33986801, 2021). "PGM5 has been found to be down-regulated in colorectal cancers." (PMID 29088828, 2017). "Furthermore, PGM5 inhibits the growth and migration of colorectal cancer cells." (PMID 33986801, 2021). "However, the expression and function of PGM5 in colorectal cancer (CRC) remains unknown." (PMID 31582909, 2019).
liver cancer (5 papers, 2019 to 2023). An epithelial or non-epithelial malignant neoplasm that arises from the liver. "Another example was PGM5 which metabolizes glucose-1-phosphate into glucose-6-phosphate and has potential use as a diagnostic and prognostic biomarker for liver cancer." (PMID 37138773, 2023). "On the contrary, the low mRNA expression of oxoglutarate dehydrogenase-like (OGDHL) and phosphoglucomutase-like protein 5 (PGM5) was associated with poor prognosis for liver cancer." (PMID 32420386, 2020). "We also found that hepatic PGM5 expression had significant value as a diagnostic indicator of liver cancer and that patients with low hepatic PGM5 expression had poorer prognosis, in terms of OS and RFS." (PMID 31218127, 2019). "This study and several previous studies suggest that PGM5 has a role in the pathogenesis of several cancers, and has potential value as a diagnostic and prognostic biomarker for liver cancer." (PMID 31218127, 2019). "Our study of patients with liver cancer indicated that hepatic PGM5 expression was positively associated with male sex and survival, and negatively associated with advanced histologic type, histologic grade, stage, and T classification." (PMID 31218127, 2019). "We examined the hepatic expression of PGM5 in patients with liver cancer, determined its association with clinical parameters, calculated its diagnostic value using receiver operating characteristic (ROC) curves, and performed survival analysis and Cox modeling to evaluate its effect on prognosis." (PMID 31218127, 2019). "Low hepatic PGM5 expression is associated with poor prognosis in patients with liver cancer." (PMID 31218127, 2019). "PGM5 has potential use as a diagnostic and prognostic biomarker for liver cancer." (PMID 31218127, 2019). "Furthermore, we determined that hepatic PGM5 expression had a modest diagnostic value for liver cancer overall and for each of the four stages of liver cancer, suggesting it has potential use as a novel diagnostic biomarker." (PMID 31218127, 2019). "The results show that PGM5 expression was lower in tissues with liver cancer (n = 373) than in adjacent normal liver tissues (n = 50; P = 4.2 ×10−11)." (PMID 31218127, 2019). "Our future studies will examine the role of PGM5 in liver cancer of different populations and will also examine its molecular function using in vivo and in vitro experiments." (PMID 31218127, 2019). "Metabolic reprogramming is a hallmark of cancer, and we therefore examined the diagnostic and prognostic value of a metabolic enzyme, phosphoglucomutase-like protein 5 (PGM5), in liver cancer." (PMID 31218127, 2019). "Relationship between the clinical features and PGM5 expression in liver cancer patients." (PMID 31218127, 2019). "Phosphoglucomutase-like protein 5 (PGM5, also called aciculin), which metabolizes glucose-1-phosphate into glucose-6-phosphate, may play an important role in liver cancer." (PMID 31218127, 2019).
breast carcinoma (3 papers, 2021 to 2024). "The miR-1224-3p/PGM5 axis was found to regulate breast cancer cell proliferation and migration through aerobic glycolysis." (PMID 38408962, 2024). "Fourth, miR-1224-3p/PGM5 axis promotes breast cancer proliferation and migration and regulates expression of cell cycle- and apoptosis-related genes and EMT markers." (PMID 33986801, 2021). "MicroRNA-1224-3p (miR-1224-3p) inhibits the PGM5 level through directly targeting its 3'-untranslated region and suppresses PGM5-mediated breast cancer cell proliferation, migration, and glycolytic function." (PMID 33986801, 2021). "In breast cancer patients, PGM5 is significantly downregulated, and its low expression is a predictor of poor prognosis." (PMID 33986801, 2021). "To detect the function of PGM5 in cancer, we first investigated the clinical significance of PGM5 in breast cancer." (PMID 33986801, 2021). "Taken together, these findings indicate that miR-1224-3p mediates the proliferation and migration of breast cancer cells through PGM5." (PMID 33986801, 2021). "We found that PGM5 was downregulated in breast cancer patients and inhibited breast cancer cell proliferation, migration, and aerobic glycolysis, accompanied by altered expression of cell cycle- and apoptosis-related genes and EMT markers." (PMID 33986801, 2021). "Our results suggest the important roles of the miR-1224-3p/PGM5 axis in regulating glycolysis and breast cancer growth and progression." (PMID 33986801, 2021). "In this study, we found that miR-1224-3p promoted breast cancer cell proliferation and migration through suppression of PGM5 expression." (PMID 33986801, 2021). "In the present study, we demonstrated that miR-1224-3p enhanced glycolysis, breast cancer cell proliferation, and migration through targeting PGM5." (PMID 33986801, 2021). "Taken together, these results suggest that PGM5 is a good prognostic factor in breast cancer patients." (PMID 33986801, 2021). "Second, the level of PGM5 is significantly downregulated in breast cancer patients compared to normal breast tissue, and the expression of PGM5 is positively correlated with DFS and OS." (PMID 33986801, 2021). "Here, we show that the phosphoglucomutase (PGM) family member PGM5 promotes conversion of glucose-1-phosphate (G1P) into glucose-6-phosphate (G6P) and inhibits breast cancer cell proliferation and migration through regulating aerobic glycolysis." (PMID 33986801, 2021). "Epithelial-mesenchymal transition (EMT) was shown to play a critical role in cancer cell migration, so we detected if PGM5 also regulates EMT of breast cancer cells." (PMID 33986801, 2021). "In the current study, we found important roles for PGM5 in breast cancer cell glycolysis, proliferation, and migration, as well as prognosis of breast cancer patients." (PMID 33986801, 2021). "It has been found that the high expression of PGM5 in Human breast cancer cell lines MCF7 and ZR75-1 can inhibit LDHA and slow down cancer progression, but miR-1224-3p can directly inhibit PGM5, which leads to the proliferation and metastasis of breast cancer cells." (PMID 37204526, 2023). "Next, we investigated whether miR-1224-3p/PGM5 axis regulates breast cancer cell proliferation, migration, and invasion through glycolysis." (PMID 33986801, 2021). "Moreover, PGM5 was also significantly downregulated in the Molecular Taxonomy of Breast Cancer International Consortium (METABRIC) database." (PMID 33986801, 2021). "Importantly, PGM5 knockdown abolished the ability of miR-1224-3p inhibitor to decrease proliferation and migration of breast cancer cells." (PMID 33986801, 2021). "Taken together, our results indicate that miR-1224-3p/PGM5 axis plays important roles in breast cancer cell proliferation, migration, and aerobic glycolysis and may be a potential target for breast cancer therapy." (PMID 33986801, 2021). "Next, we detected the effect of PGM5 on proliferation and migration of breast cancer cells." (PMID 33986801, 2021).
breast carcinoma (continued). "Next, we investigated the biological function of miR-1224-3p in breast cancer cells and tested whether miR-1224-3p exhibits these functions through PGM5." (PMID 33986801, 2021). "Therefore, miR-1224-3p/PGM5 axis in breast cancer may provide new targets for developing antitumor drugs." (PMID 33986801, 2021). "Repression of miR-1224-3p or activation of PGM5 may be useful strategies for breast cancer therapy." (PMID 33986801, 2021). "However, how PGM5 expression is regulated, and whether PGM5 regulates glycolysis and breast cancer development and progression remains unclear." (PMID 33986801, 2021). "Cytological experiments demonstrated that overexpression of PGM5 inhibited proliferation, migration and epithelial-mesenchymal transition (EMT) of breast cancer cells." (PMID 38408962, 2024). "The level of PGM5 was decreased in breast cancer patients compared to the adjacent nontumor normal tissues in the Cancer Genome Atlas (TCGA) breast cancer (BRCA) database." (PMID 33986801, 2021). "However, the function of PGM5 in breast cancer has not been reported." (PMID 33986801, 2021).
bladder cancer (2 papers, 2019 to 2021). "PGM5 expression was similarly down-regulated in bladder cancer tissues, but validation in 34 pairs of tissues showed that PGM5 expression in cancer and adjacent tissues was not significantly different (up-regulation in 15 cases and down-regulation in 19 cases)." (PMID 31582909, 2019).
colorectal adenoma (2 papers, 2017 to 2019). An adenoma that arises from the colon or rectum. "Recent studies have shown that PGM5 is down-regulated in colorectal adenomas or adenocarcinomas." (PMID 31582909, 2019). "In CRC, PGM5 was also reported as a potential protein marker of colorectal adenoma." (PMID 28797257, 2017).
prostate carcinoma (2 papers, 2022 to 2024). A carcinoma that arises from epithelial cells of the prostate gland. "Taken together, our findings provide the first evidence that PGM5 expression is associated with prostate cancer progression, which suggest PGM5 as a promising prognostic marker and therapeutic target in prostate cancer." (PMID 35819729, 2022). "Taken together, our findings provide the first evidence that PGM5 expression is associated with prostate cancer progression." (PMID 35819729, 2022). "In the present study, our results demonstrate that PGM5 expression is decreased in primary and metastatic prostate cancer by bioinformatic analyses and immunohistochemical assessment, which indicate a novel role for PGM5 as an important diagnostic and prognostic marker in prostate cancer." (PMID 35819729, 2022). "We found a much lower level of methylation in CpG island in normal tissues than that of prostate cancer tissues, which also suggests that DNA methylation is likely to be one of the important mechanisms for downregulation of PGM5 expression." (PMID 35819729, 2022). "Most of the results are preliminary, such as the mechanisms of PGM5 downregulation in prostate cancer." (PMID 35819729, 2022). "To analyze the value of PGM5 in the diagnosis and disease prognosis of prostate cancer, we performed ROC curve analysis for PGM5 in healthy individuals and in PCa patients, or in primary cancer and in metastatic cancer." (PMID 35819729, 2022). "Here, we reported that the expression of phosphoglucomutase-like protein 5 (PGM5) is significantly lower in prostate cancer tissue." (PMID 35819729, 2022). "To further investigate the effect of PGM5 downregulation on the development of prostate cancer, we analyzed the effects of PGM5 downregulation on various gene sets by the GSEA." (PMID 35819729, 2022). "In vitro assays showed that overexpression of PGM5 significantly repressed proliferation and migration of prostate cancer cells." (PMID 35819729, 2022). "Considering the important role of PGM5 downregulation in prostate cancer disease progression, we further analyzed the mechanisms of decreased PGM5 expression and conducted preliminary investigation." (PMID 35819729, 2022). "Our database analysis showed that high PGM5 methylation level is correlated with low PGM5 expression level in prostate tumors and with poor prognosis in prostate cancer patients." (PMID 35819729, 2022). "We utilized a series of online RNA-seq data to explore the role of PGM5 in prostate cancer by bioinformatics analysis." (PMID 35819729, 2022). "We further used immunohistochemistry to evaluate the expression of PGM5 protein in a wide spectrum of prostate tissues to determine its expression in situ, and evaluated the prognostic value of PGM5 in prostate cancer." (PMID 35819729, 2022). "We summarized the gene expression data of several authoritative prostate cancer clinical sequencing databases and found PGM5 downregulation in tumor tissues in all datasets." (PMID 35819729, 2022). "We first investigated the relationship between PGM5 expression and the clinic pathological characteristics in the TCGA prostate cancer dataset using cBioPortal for Cancer Genomics." (PMID 35819729, 2022). "We finally found in multiple databases that PGM5 is a gene that is down-regulated with prostate cancer development." (PMID 35819729, 2022). "Further analysis indicated the tumor suppressor role of PGM5 in prostate cancer, which was also confirmed by in vitro assays and IHC in tumor tissues from our patients." (PMID 35819729, 2022). "Methylation of PGM5 might be a potential prostate cancer research and drug target, which also needs further molecular biological experiments to validate." (PMID 35819729, 2022). "We examined PGM5 protein expression by IHC in prostate cancer and matched para-cancer tissues." (PMID 35819729, 2022). "The expression and function of PGM5 in cancer, especially in prostate cancer is still largely unknown." (PMID 35819729, 2022).
prostate carcinoma (continued). "This suggested that PGM5 downregulation may affect disease progression and prognosis in prostate cancer patients by influencing cell cycle, DNA repair and multiple oncologic pathways, which could be further explored and confirmed in future analysis." (PMID 35819729, 2022). "In conclusion, we found the expression of PGM5 is significantly lower in prostate cancer tissue." (PMID 35819729, 2022). "Thus, our findings above indicated that PGM5 expressed much lower in prostate cancer tissue, which makes it a potential biomarker for prostate cancer development." (PMID 35819729, 2022). "As for how PGM5 downregulated in prostate cancer initiation and development, our results suggest DNA methylation might be the potential mechanism." (PMID 35819729, 2022). "To further explore the mechanisms of PGM5 in prostate cancer and find out some testable hypotheses, we did the correlation analysis using the datasets from NCBI-GEO above." (PMID 35819729, 2022). "To test the hypothesis that the methylation of DNA could play a role in regulating PGM5 expression in prostate cancer, we explored the correlation between PGM5 methylation and PGM5 expression in TCGA dataset by cBioPortal for Cancer Genomics." (PMID 35819729, 2022). "We next determined whether PGM5 expression influences prostate cancer progression." (PMID 35819729, 2022). "To further investigate the role of PGM5 in prostate cancer progression, we overexpressed PGM5 in LNCaP, DU145 and PC-3 prostate cancer cell lines." (PMID 35819729, 2022). "Through the analysis of seven datasets (TCGA, GSE30521, GSE4602, GSE55945, GSE69223 GSE104131, and GSE200879), we identified two upregulated genes (AMACR and GCNT1) and seven downregulated genes (TGFB3, SRD5A2, PGM5, HOXD10, AOX1, HSPB6, and SNAI2) in prostate cancer compared to normal tissue." (PMID 38374143, 2024).
skeletal myopathies (2 papers, 2020 to 2024). "The similar importance of PGM5 in fish was demonstrated in a PGM5 knockdown zebrafish where the embryos developed severe cardiac and skeletal myopathy and showed indications of paralysis." (PMID 33287293, 2020). "In addition, zebrafish embryos have been found to develop severe cardiac and skeletal myopathies with signs of paralysis after knocking out the gene for PGM5." (PMID 38433959, 2024).
stomach cancer (2 papers, 2019 to 2020). "Another example of a conservative mutation in human PGM5 that has a dramatic effect is the somatic oncogenic mutation Ile98Val associated with stomach cancer." (PMID 33287293, 2020). "Similarly, phosphoglucomutase-like protein 5 (PGM5) had a hotspot mutation (I98V) in stomach cancer and the 10th highest score." (PMID 31345222, 2019).
Alzheimer disease (1 paper, 2023). A progressive, neurodegenerative disease characterized by loss of function and death of nerve cells in several areas of the brain leading to loss of cognitive function such as memory and language. "Phosphoglucomutase 5 is predominantly found in adherens junctions, which are believed to be involved in blood–brain barrier (BBB) permeability regulation in Alzheimer’s disease." (PMID 37872607, 2023).